OFD1 (OFD1 centriole and centriolar satellite protein)
Description:
Component of the centrioles controlling mother and daughter centrioles length. Recruits to the centriole IFT88 and centriole distal appendage-specific proteins including CEP164 (By similarity). Involved in the biogenesis of the cilium, a centriole-associated function. The cilium is a cell surface projection found in many vertebrate cells required to transduce signals important for development and tissue homeostasis. Plays an important role in development by regulating Wnt signaling and the specification of the left-right axis. Only OFD1 localized at the centriolar satellites is removed by autophagy, which is an important step in the ciliogenesis regulation (By similarity).
Synonyms: CXorf5; 71-7A; JBTS10; RP23; SGBS2
Tractability: Antibody: its Gene Ontology location is reachable by antibodies, with medium confidence. PROTAC: UniProt records ubiquitination sites on it; ubiquitination databases record sites on it; its protein half-life has been measured.
Gene: Protein-coding gene on chromosome X (13,734,675 to 13,777,955, forward strand). Ensembl gene ENSG00000046651.
Subcellular location: Cytoplasm, cytoskeleton, microtubule organizing center, centrosome, centriole; Cytoplasm, cytoskeleton, cilium basal body; Nucleus; Cytoplasm, cytoskeleton, microtubule organizing center, centrosome, centriolar satellite
Subcellular location (Human Protein Atlas): Microtubules; End piece; Primary cilium
Pathways (Reactome):
Cell Cycle: AURKA Activation by TPX2; Loss of Nlp from mitotic centrosomes; Loss of proteins required for interphase microtubule organization from the centrosome; Recruitment of NuMA to mitotic centrosomes; Recruitment of mitotic centrosome proteins and complexes; Regulation of PLK1 Activity at G2/M Transition
Organelle biogenesis and maintenance: Anchoring of the basal body to the plasma membrane
Signal Transduction: Hedgehog 'off' state
Gene Ontology:
Molecular function: identical protein binding; molecular adaptor activity; protein binding; alpha-tubulin binding; gamma-tubulin binding
Biological process: cilium assembly; centriole replication; epithelial cilium movement involved in determination of left/right asymmetry; mitotic cell cycle; mitotic spindle assembly; embryonic body morphogenesis
Cellular component: centriole; centrosome; ciliary basal body; cilium; membrane; nucleus; centriolar satellite; cytosol; motile cilium; extracellular region
Gene-disease validity (ClinGen):
ClinGen rates the evidence that OFD1 causes each of these diseases.
OFD1-related ciliopathy (X-linked): Definitive. Any ciliopathy caused by monoallelic, biallelic, or hemizygous variants in the OFD1 gene.
Homologues: Orthologues: chimpanzee OFD1 (99% identical), macaque OFD1 (96% identical), dog OFD1 (71% identical), rat Ofd1 (69% identical), mouse Ofd1 (67% identical), guinea pig OFD1 (67% identical), tropical clawed frog ofd1 (41% identical), zebrafish ofd1 (32% identical).
Diseases named in the same sentence as OFD1 in open-access papers:
OFD1 is named in the same sentence as 100 diseases in open-access papers, as found by Europe PMC text mining. Sharing a sentence is not in itself a finding about the gene and the disease. The quoted sentences say what the papers report.
ciliopathy (33 papers, 2012 to 2025). A genetic disorder of the cellular cilia or the cilia anchoring structures, the basal bodies, or of ciliary function. "Mutations in OFD1 cause several disorders, which affect primary and/or motile cilia (ciliopathies), and therefore manifest in multiple tissues." (PMID 39940934, 2025). "In this study, we showed that knockdown of ik induced ciliopathy phenotypes with disrupted ciliogenesis, which was accompanied by downregulation of ciliopathy-associated gene ofd1." (PMID 37898820, 2023). "Missense mutations within the LisH domain of OFD1, including the E97G substitution, are causally linked to sporadic forms of ciliopathy." (PMID 33934390, 2021). "We found that the E97G mutation alters the proteolytic turnover of OFD1 in cells stimulated with cAMP, suggesting a pathogenic role of altered proteostasis of OFD1 in certain forms of ciliopathy disorders." (PMID 33934390, 2021). "Heterozygous loss-of-function mutations in OFD1 produce the OFD1 syndrome, an X-linked dominant disorder lethal in males that is characterized by systemic ciliopathy features." (PMID 34207779, 2021). "Of note, OFD1 mutations have recently been associated to novel phenotypes outlining the wide phenotypic spectrum of ciliopathies." (PMID 33825116, 2021). "OFD1 is involved in cilia formation, with gene defects affecting multiple tissues, and ciliopathies have been implicated in fertility issues." (PMID 26560630, 2016). "His Ciliopathy Panel showed a likely pathogenic deletion, approximately 7.9 kb, in the OFD1 gene encompassing exons 16, 17, and 19 (c.1654+833_2599+423del) which is a novel mutation." (PMID 27651963, 2016). "A Ciliopathy Panel showed a novel and likely pathogenic deletion, approximately 7.9 kb, in the OFD1 gene encompassing exons 16, 17, and 19 (c.1654+833_2599+423del)." (PMID 27651963, 2016). "It is likely that the differences in primary cilia defect between Ta3 and Ofd1 mutants and/or other cilia-independent roles could also account for the differences between these and other ciliopathy-associated genes." (PMID 39682705, 2024). "As the ofd1 expression was downregulated in loss of ik leading to ciliopathy phenotypes, further experiments are required to address whether loss of ofd1 enhances autophagy in ik mutants." (PMID 37898820, 2023). "OFD1 syndrome is a well-known ciliopathy caused by mutations of OFD1." (PMID 38139355, 2023). "Further understanding of the molecular mechanisms underlying the functional interactions between OFD1 and autophagy will be of utmost importance not only from a basic science point of view but also for the possible therapeutic implications for ciliopathies and other conditions." (PMID 33681704, 2021). "OFD1 E97G mutation is causally linked to a sporadic form of ciliopathy." (PMID 33934390, 2021). "Our studies could ultimately link defects in Talpid3 function to Joubert Syndrome and other lethal ciliopathies and explain the spectrum of pathologies associated with human mutations in OFD1 and C2CD3." (PMID 30258116, 2018). "Mutations in OFD1 may lead to reduced levels of normal ciliopathy protein and be related to retinal degeneration." (PMID 28191358, 2017). "In this report, we focus on OFD1, a cilioprotein shown to be involved in the formation of cilia and establishment of left–right asymmetry, which has been implicated in primary and motile ciliopathies presenting phenotypes ranging from isolated retinitis pigmentosa to multiorgan involvement." (PMID 35112477, 2022). "In particular, OFD1 is the first example of a ciliopathy protein that controls protein expression and autophagy/proteasome degradation, providing directions for the treatment of various diseases." (PMID 38410514, 2024). "CEP90 is essential for cilium assembly in mammalian cells and forms part of a ciliopathy complex with OFD1, which is located at the distal end of mother centrioles in mammals." (PMID 38572631, 2024).
ciliopathy (continued). "Our findings on the ik–ofd1 axis provide new insights into the biological function of ik in clinical ciliopathy studies in humans." (PMID 37898820, 2023). "Variants in PKD1 and PKD2 comprised 85.3% of the positive findings in this group, and other ciliopathy-associated genes (ALG9, PRKCSH, OFD1) accounted for an additional 3%." (PMID 37794564, 2023). "Orofaciodigital syndrome I (OFD1–MIM #311200) is a rare ciliopathy characterized by facial dysmorphism, oral cavity, digit, and brain malformations, and cognitive deficits." (PMID 36833254, 2023). "In 2009, the OFD1 transcript was also implicated in an X‐linked recessive form of Joubert syndrome (JBS10; MIM #300804), a ciliopathy affecting primary cilia." (PMID 35112477, 2022). "More recently, mutations in the OFD1 transcript were also identified in patients affected by PCD (MIM #244400), which is a motile ciliopathy mainly affecting the respiratory epithelium and the reproductive tract." (PMID 35112477, 2022). "The zebrafish ofd1 morphants also displayed laterality defects, due to cilia abnormalities in the Kupffer ́s vesicle, as well as additional ciliopathy features." (PMID 34207779, 2021). "By controlling OFD1 levels, this regulatory circuitry deeply impacts on cilium biology and development, with important implication for ciliopathies and proliferative disorders." (PMID 33934390, 2021). "We propose a novel model that explains how TRAPPIII regulates ciliogenesis via its interaction with a ciliopathy protein, OFD1." (PMID 32258032, 2020). "We found a ciliopathy protein, oral-facial-digital syndrome 1 (OFD1), interacting with the TRAPPIII-specific subunits TRAPPC8 and TRAPPC12." (PMID 32258032, 2020). "Other ciliopathy proteins including BBS1,2,4,6,7,8, NPHP5 and OFD1 also interact with proteasomal components, while loss of BBS4, BBS7 and OFD1 also resulted in a decrease of proteasomal activity." (PMID 29796181, 2018). "Biallelic mutations in the ciliopathy-associated genes AHI1, BBS10, IQCB1, and OFD1 were identified in single patients." (PMID 29974258, 2018). "Mutations in these ciliary genes are implicated in photoreceptor degeneration related ciliopathies, such as RPGRIP1 in cone dystrophy (CD)/cone-rod dystrophy (CRD), LCA5 and CEP290 in Leber congenital amaurosis (LCA), Fam161A and OFD1 in RP." (PMID 27196396, 2016). "Based on this unusual presentation, we recommend that OFD1 screening be considered, even in males, if the suspicion for ciliopathy remains high in families with features of OFD1 in female members." (PMID 27651963, 2016). "We show that this complex consists of the polycystins (PC1 and PC2), the OFD1 ciliopathy disease gene product, the EGFR receptor tyrosine kinase and the membrane raft organizing flotillin proteins." (PMID 25180832, 2014). "The severity of OFD1-related ciliopathies largely depends on the size of protein truncation." (PMID 39940934, 2025). "Interestingly, five of the potential interactors (PIBF1, CSPP1, OFD1, C2CD3, and KIF7) have been linked to a single ciliopathy, the Joubert syndrome, reinforcing the role of CCP6 activity in cilia regulation." (PMID 36674791, 2023). "Next, to determine whether ofd1 could rescue the ciliopathy phenotypes in ik mutants, we analyzed the phenotypes of ik morphants co-injected with ofd1 mRNA." (PMID 37898820, 2023). "These are clinical features consistent with a syndromic ciliopathy, and we are not aware of any previous reports of males with hemizygous OFD1 variants having this combination of features." (PMID 35764379, 2022). "Several ciliopathy-associated proteins, including Bardel Biedl syndrome 4 (BBS4), CEP290, pericentriolar material 1 (PCM1), and orofaciodigital syndrome 1 (OFD1), localize to centriolar satellites and are critical for cargos entry and/or exit from the primary cilium." (PMID 32258032, 2020).
ciliopathy (continued). "In our recent study we revealed the molecular mechanisms underlying the direct functional role of the centrosomal/basal body protein OFD1, in LC3-mediated autophagy control, and the far-reaching implications for ciliopathies." (PMID 33681704, 2021). "The OFD1 (oral-facial-digital 1) gene was initially identified in oral-facial-digital syndrome (OMIM 311200) and is responsible for other ciliopathies such as Joubert syndrome, Simpson-Golabi-Behmel syndrome type 2, and retinitis pigmentosa (RP)." (PMID 27196396, 2016). "Some ciliopathy proteins, such as BBS4, CEP290 and OFD1, are constituents of centriolar satellites." (PMID 23110211, 2012).
Joubert syndrome (14 papers, 2011 to 2025). Joubert syndrome (JS) is characterized by congenital malformation of the brainstem and agenesis or hypoplasia of the cerebellar vermis leading to an abnormal respiratory pattern, nystagmus, hypotonia, ataxia, and delay in achieving motor milestones. "He carried the OFD1 mutation p.Gln886Lysfs*2 (NM_003611.2: c.2656del) and manifested features of Joubert syndrome." (PMID 28344780, 2017). "In more recent years mutation in the OFD1 transcript have also been identified in patients with Joubert syndrome, a ciliopathy characterized by extensive neuropathological findings." (PMID 23300826, 2012). "The OFD1 gene mutation is reportedly related to four syndromes with X chromosome-linked recessive inheritance (Joubert syndrome, retinitis pigmentosa, primary ciliary dyskinesia, and Simpson-Golabi-Behmel syndrome), which have phenotypes observed in both males and females." (PMID 36362756, 2022). "The different locations of OFD1 variants cause three different syndromes: OFDSI (exons 2–17), Simpson–Golabi–Behmel syndrome type 2 (exon 16), and Joubert syndrome 10 (exons 17–22)." (PMID 39156004, 2024). "The identified variant, p.(Gln892Ter) in patient #2, may result in the synthesis of a truncated protein, potentially affecting OFD1 protein function differently than what is observed in the cases of PCD or Joubert syndrome." (PMID 39766900, 2024). "Mutations in the OFD1 gene with different degrees of severity may cause oro-facio-digital-syndrome 1 (OFD1 syndrome, MIM 311200), Joubert syndrome (JBS10), retinitis pigmentosa (RP23, MIM 300424) and primary ciliary dyskinesia (PCD, MIM 244400)." (PMID 36704348, 2022). "Notably, some studies suggest that certain LoF variants located in the last exons of the OFD1 gene may escape nonsense-mediated decay (NMD), leading to phenotypes such as Joubert syndrome or isolated PCD." (PMID 39766900, 2024). "In summary, the current study extends our knowledge regarding the role of the basal body protein Ofd1 in forebrain development and may help explaining the neuropathological findings observed in patients bearing mutations in the OFD1 transcript and affected by OFD type I and Joubert syndromes." (PMID 23300826, 2012). "Intriguingly, five of the candidate interactors found in our BioID-based interactomic study (i.e., C2CD3, PIBF1, CSPP1, OFD1, and KIF7) are related to a single rare pathology, the Joubert syndrome." (PMID 36674791, 2023). "Published OFD1 mutations cause a spectrum of X-linked ciliopathies, inherited as dominant (OFDS1) or recessive conditions (Joubert syndrome (JBTS10) and Simpson-Golabi-Behmel syndrome 2 (SGBS2))." (PMID 32577127, 2020).
cystic kidney disease (10 papers, 2014 to 2026). A congenital or acquired kidney disorder characterized by the presence of renal cysts. "Encephalocele, hydrocephalus, macrocephaly, MCD, polydactyly, renal cystic disease, retinal disease, and tetralogy of Fallot are observed in OFD1-related JS." (PMID 36468023, 2022). "Cilia dysfunction is commonly observed in models of renal cystic disease and has been described in mutant kidneys of different Ofd1-inactivated in vivo models." (PMID 32077937, 2020). "If, as it seems, the hemizygous male cannot survive without OFD1, how do we explain the 14‐year old male twins with a missense mutation in exon 19 and renal cystic disease as the only clinical sign (H.‐W." (PMID 35112477, 2022). "OFDS type 1 (OFD1, MIM 311200) is an X-linked dominant ciliopathy caused by mutations in OFD1 gene, involved in ciliogenesis and cilia length regulation, and it is distinguished from other OFDS subtypes by adult-onset cystic kidney disease in addition to its inheritance pattern." (PMID 33748110, 2021). "Interestingly, Ofd1 and Bicc1 are both involved in renal cystogenesis and selected targets were shown to accumulate in two models of inherited renal cystic disease." (PMID 28450740, 2017). "While the OFD1 protein localizes to centriolar satellites, centrosomes and basal bodies, its cellular function and how it relates to cystic kidney disease is largely unknown." (PMID 25180832, 2014). "For example, conditional inactivation of the transcript in the kidneys demonstrated that cilia are initially present in the Ofd1‐inactivated renal epithelial cells and disappear when renal cysts form suggesting that the disappearance of cilia could be a secondary event." (PMID 35112477, 2022). "While OFD1 weakly binds mRNA, the presence of BICC1, an RNA-binding protein also found at the centrosome, allows OFD1 to mediate a stronger association between eIF4F via eIF4E and several centrosomal mRNAs that are implicated in ciliogenesis and renal cyst formation." (PMID 34805187, 2021).
orofaciodigital syndrome I (8 papers, 2014 to 2024). "OFD1 mutations have been reported to cause X-linked recessive Joubert syndrome, orofaciodigital syndrome and isolated RP." (PMID 29843741, 2018). "Pathologic variation in OFD1 is the cause of orofaciodigital syndrome (MIM 311200), which can include congenital heart malformations within its phenotypic spectrum." (PMID 29089047, 2017). "Mutations in OFD1 cause orofaciodigital syndrome 1 (MIM 311200), which in 40% of cases includes central nervous system anomalies, including the absence of the corpus callosum." (PMID 24476948, 2014). "Orofaciodigital syndrome I (OFD1-MIM #311200) is a rare, complex, and clinically variable disorder characterized by facial dysmorphism and malformations of the oral cavity (mouth, tongue, and teeth) and digits." (PMID 36833254, 2023). "In human ciliated cells, IFT88 (OMIM: 600,595) co-localizes with OFD1 (OMIM: 300,170), and genetic alterations in OFD1 cause Orofaciodigital Syndrome-1." (PMID 35145545, 2021). "Several diagnostic hypotheses led to the non-conclusive exploration of GLI3 (Pallister-Hall), OFD1 (Orofaciodigital syndrome I) and the known BBS genes at that time (BBS1-BBS18) using Sanger and targeted exome sequencing." (PMID 30761183, 2019).
retinitis pigmentosa (8 papers, 2016 to 2023). Retinitis pigmentosa (RP) is an inherited retinal dystrophy leading to progressive loss of the photoreceptors and retinal pigment epithelium and resulting in blindness usually after several decades. "Ofd1 is a newly identified causative gene for Retinitis pigmentosa (RP), a photoreceptor degenerative disease." (PMID 27196396, 2016).
oral-facial-digital syndrome (7 papers, 2016 to 2026). "Ofd1, a protein mutated in oral-facial-digital syndrome, co-localizes with C2cd3 at the distal centriole." (PMID 27114821, 2016). "Oral-facial-digital 1 (ofd1) is the first gene reported in oral-facial-digital syndrome (OMIM 311200) and encodes OFD1 protein located in the centrosome and basal body of primary cilia." (PMID 37898820, 2023). "Indeed KIAA0753, which falls within our 25% cFDR list of cilium genes, was shown to interact with OFD1 and FOR20 at pericentriolar satellites and centrosomes, and gives rise to oral-facial-digital syndrome, a phenotype associated with disruption in the ciliary transition zone and the basal body." (PMID 31095607, 2019).
primary ciliary dyskinesia (7 papers, 2022 to 2025). A rare, genetically heterogeneous, primarily respiratory disorder characterized by chronic upper and lower respiratory tract disease. "OFD1 mutations known to cause oral–facial–digital syndrome type 1 can occur in patients with ciliary dyskinesia and situs inversus." (PMID 37555648, 2023).
oral-facial-digital syndrome 1 (6 papers, 2019 to 2023). "IFT88 overexpression led to upregulation of IFT80/81, two critical components of IFTB complex, and caused downregulation of OFD1 (oral-facial-digital syndrome 1), a ciliogenesis suppressor." (PMID 37485393, 2023). "Mutations of OFD1 gene cause Orofaciodigital syndrome type 1 (OFDI), distinguished from the other Orofaciodigital syndromes by X-linked dominant inheritance and cystic kidney disease." (PMID 32276433, 2020). "OFD1, a gene underlying oral-facial-digital syndrome 1, controls the length of centrioles." (PMID 35428183, 2022).
cystic kidneys (5 papers, 2016 to 2026). "There have been reports of cystic kidneys being more frequently associated with splice mutations and with mutations located in exons 9 and 12 on the OFD1 gene." (PMID 27651963, 2016).